NFATC3 (nuclear factor of activated T cells 3)
Diseases named in the same sentence as NFATC3 in open-access papers (continued):
Sharing a sentence is not in itself a finding about the gene and the disease.
Sepsis (2 papers, 2018 to 2023). Sepsis is defined as life-threatening organ dysfunction caused by a dysregulated host response to infection. "The cellular role of NFATc3-deficient macrophages in sepsis-induced ALI pathogenesis and pulmonary edema development is strongly supported by using novel high efficacy peptide inhibitors of NFATs in mouse lungs." (PMID 29535830, 2018). "To test this hypothesis, we characterized NFATc3 deficient and WT macrophages and measured the outcomes of sepsis-induced ALI in NFATc3−/− and WT mice." (PMID 29535830, 2018). "NFATc3−/− and WT mice were subjected to severe sepsis by using a lethal model of CLP and were monitored for survival over 96 h." (PMID 29535830, 2018). "We observed that in vitro treatment with LPS, an inducer of sepsis-like pathophysiology in mice, results in induction of NFATc3 activation in macrophages." (PMID 29535830, 2018). "Since macrophages with altered expression levels of TNFα, CCR2 and iNOS are expected to affect lung inflammation, homeostasis and host resistance, we determined the functional implication of NFATc3 deletion on sepsis-induced ALI in mouse CLP sepsis models." (PMID 29535830, 2018). "Current study using NFATC3−/− mice lead to an important finding that NFATc3 plays a pivotal role in the pathogenesis of sepsis induced ALI and pulmonary edema in murine models of sepsis." (PMID 29535830, 2018). "We have examined the gene targets of sepsis in macrophages and discovered that NFATc3 is activated during sepsis and regulates expression of induced Nitric Oxide Synthase." (PMID 29535830, 2018). "In summary, our study supports the conclusion that NFATc3 has a pivotal role in mediating sepsis-induced ALI pathogenesis and pulmonary edema." (PMID 29535830, 2018). "To confirm the in vivo results observed in the NFATc3-deficient mice, we next aimed to determine whether pharmacological inhibition of NFAT by a VIVIT expressing plasmid attenuates sepsis-induced ALI." (PMID 29535830, 2018). "More importantly, NFATc3 deficient mice showed decreased neutrophilic lung inflammation, improved alveolar capillary barrier function, arterial oxygen saturation and survival benefit in lethal CLP sepsis mouse models." (PMID 29535830, 2018). "Thus, this study demonstrates that inhibition of NFATc3 activation by CP9-ZIZIT provides a potential therapeutic option for attenuating sepsis induced ALI/pulmonary edema." (PMID 29535830, 2018). "Interestingly, NFATc3-deficient macrophages when stimulated with LPS showed attenuated expression of several cytokines, chemokines, and their receptors, thus translating to a profound phenotypic effect of NFATc3 deletion in sepsis induced ALI." (PMID 29535830, 2018). "Comparison of LPS stimulated NFATc3−/− and WT BMDM gene expression indicated distinct down regulation of LPS induced CCR2 and TNFα in NFATc3−/− macrophages, suggesting that NFATc3 regulates macrophage gene expression thereby regulates pathogenesis of sepsis induced-ALI." (PMID 29535830, 2018). "Most importantly our data suggest that inhibition of NFATc3 and broad spectrum antibiotics could be used in combination in patients with severe sepsis." (PMID 29535830, 2018). "In addition, survival of wild type mice subjected to the lethal CLP sepsis was not improved with broad-spectrum antibiotics, whereas the survival of NFATc3 deficient mice was improved to 40–60% when treated with imipenem." (PMID 29535830, 2018). "Previously, we have demonstrated that NFATc3 regulates macrophage effector functions by regulating different cytokines, CCR2, and iNOS during sepsis and acute lung injury." (PMID 37523510, 2023). "We have reported a pivotal role for Nuclear Factors of Activated T cells (NFATc3) in regulating macrophage phenotype during sepsis induced ALI and subsequent studies demonstrate that NFATc3 transcriptionally regulates macrophage CCR2 and TNFα gene expression." (PMID 29535830, 2018).
Sepsis (continued). "NFATc3 deletion showed decreased pulmonary edema, neutrophilic inflammation, improved arterial oxygenation and survival during CLP-induced sepsis in mice." (PMID 29535830, 2018). "Similar to NFATc3−/− mice, CP9-ZIZIT pretreated mice showed decreased pulmonary edema, BALF cytokines and lung wet to dry ratios during sepsis-induced ALI." (PMID 29535830, 2018). "NFATc3 activation and its functional significance in sepsis-induced ALI have not been examined in macrophages that are critical innate immune cells involved in ALI pathogenesis." (PMID 29535830, 2018).
acute lung injury (1 paper, 2024). A condition of lung damage that is characterized by bilateral pulmonary infiltrates (pulmonary edema) rich in neutrophils, and in the absence of clinical heart failure. "Inhibition of NFATc3 activation by a novel cell-permeable calcineurin peptide inhibitor CNI103 mitigated the development of acute lung injury (ALI) in LPS-treated mice." (PMID 38812883, 2024).
adenoma (1 paper, 2024). A neoplasm arising from the epithelium. "Adenomas had significantly increased expression of transcription factors E2f5 and Tcf712, Wnt family receptor Fzd2, transcriptional regulator Nfatc3, regulator of the gamma secretase complex Psenen, and Rb." (PMID 38334641, 2024).
aortic aneurysm (1 paper, 2025). A ruptured aneurysm located in the wall of the proximal portion of the descending aorta proceeding from the arch of the aorta. "This study investigated the role of the nuclear factor of activated T cells c3 (NFATc3) in vascular smooth muscle cells (VSMCs) during aortic aneurysm and dissection (AAD) progression and the underlying molecular mechanisms." (PMID 40698138, 2025). "To investigate whether NFATc3 expression is associated with aortic aneurysm, we re-analyzed the single-cell RNA sequencing GEO database (GSE155468) generated from aortic tissue from patients with healthy ascending aortic tissue or diagnosed with TAA." (PMID 40698138, 2025).
Arrhythmia (1 paper, 2014). Any cardiac rhythm other than the normal sinus rhythm. "The inhibition of Ca2+/Calcineurin/NFatc3 signalling pathway may partially explain the decrease in arrhythmia susceptibility." (PMID 24780005, 2014).
astroglioma (1 paper, 2022). "Furthermore, it is implicated that NFATC3 influences tumor growth in human astroglioma." (PMID 35332692, 2022).
B cell lymphopenia (1 paper, 2019). "The severe B cell lymphopenia observed in the absence of NFATc1 activity was not present in mice that were deficient in NFATc2, NFATc3, or both." (PMID 29907883, 2019).
B-cell lymphomas (1 paper, 2014). "In addition, NFATC3 was hypothesized as being part of a mechanism whereby intratumoural CD4+CD25+ T-cells (Treg cells) interact with activated CD4+ T-cells to suppress the anti-tumour activity of infiltrated CD4+ T-cells in B-cell NHL tumours and thus, induce immune tolerance to these tumours." (PMID 24885312, 2014). "Moreover, the abrogation of NFATC3 expression in a murine model suggested the implication of this TSG in T-cell lymphomagenesis; whereas, its implication in B-cell lymphomas has not been studied." (PMID 24885312, 2014).
Cognitive impairment (1 paper, 2023). Abnormal cognition is characterized by deficits in thinking, reasoning, or remembering. "Among the 52 inflammatory/immune proteins positively correlated with EDII score, six proteins (CXCL10, CCL3, HGF, OPG, CDCP1, NFATC3) were significantly associated with increased odds of incident cognitive impairment after adjusting for demographic characteristics and cardiovascular risk factors." (PMID 36737481, 2023). "Results provide insights into how inflammatory nutritional patterns are associated with an immune-related proteome and identify a group of proteins (CXCL10, CCL3, HGF, OPG, CDCP1, NFATC3, ITGA11) related to future cognitive impairment over a 14-year follow-up period." (PMID 36737481, 2023). "In addition to demonstrating their relationship to inflammatory diet and incident cognitive impairment/dementia, we identified OPG, HGF, NFATC3, CDCP1, and ITGA11 as differentially expressed at the RNA level in brain tissue of deceased individuals with pathologically defined AD." (PMID 36737481, 2023).
cutaneous melanoma (1 paper, 2019). A primary melanoma arising from atypical melanocytes in the skin. "Our study also proposes genes ESM1, NFATC3, C7orf4, CDK14, ZNF827, and ZSWIM7 as novel putative markers for cutaneous melanoma metastasis." (PMID 31673075, 2019).
dysplasia (1 paper, 2019). A usually neoplastic transformation of the cell, associated with altered architectural tissue patterns. "Mean IHC scores for NFATc3 in NHOE, dysplasia, and OSCC were 1.30, 2.0, and 2.54, respectively, showing statistical significant difference." (PMID 31040921, 2019).
epilepsy (1 paper, 2024). A brain disorder characterized by episodes of abnormally increased neuronal discharge resulting in transient episodes of sensory or motor neurological dysfunction, or psychic dysfunction. "In summary, this evidence makes NFATC3 a promising epilepsy candidate gene." (PMID 38383918, 2024).
esophageal cancer (1 paper, 2019). A primary or metastatic malignant neoplasm involving the esophagus. "In parallel, TRPM8-calcineurin-induced NFATc3 activation was involved in the pathogenesis of esophageal cancer as we proved." (PMID 31519770, 2019). "More importantly, our findings indicated NFATc3 contributed to immune evasion of esophageal cancer cells." (PMID 31519770, 2019). "Our results showed that blocking the activity of calcineurin inhibited the nuclear translocation of NFATc3 and PD-L1 expression in esophageal cancer cells, which inferred a contributing role of TRPM8-calcineurin-NFATc3 in the expression of PD-L1." (PMID 31519770, 2019). "Finally, we proved that TRPM8 regulated PD-L1 expression by calcineurin-NFATc3 pathway in esophageal cancer cells." (PMID 31519770, 2019). "Finally, we explored the mechanism and found that calcineurin-nuclear factor of activated T cells 3 (NFATc3) pathway contributed to the expression of programmed death ligand 1 (PD-L1) induced by TRPM8 overexpression and TRPM8 agonist, which might lead to immune evasion of esophageal cancer cells." (PMID 31519770, 2019).
head and neck cancer (1 paper, 2022). A primary or metastatic malignant neoplasm affecting the head and neck. "After analyzing the overexpression of TRPM7, NFATC3, and Notch1 within different head and neck cancer cell lines, we screened cell lines suitable for subsequent experiments." (PMID 35771152, 2022).
lymphopenia (1 paper, 2018). Reduction in the number of lymphocytes. "In contrast, DEGs found exclusively during EBOV infection were mostly involved with dysregulation of blood circulation and vasculature development as well as lymphopenia as evidenced by a decrease in CD79B, CD3, CD8, NFATC3, and PRF1." (PMID 30723475, 2018).
mastitis (1 paper, 2022). Inflammation of breast tissue during lactation or postpartum due to an obstructed duct or infection. "Some positively selected genes were reported to be associated with lactation function and disease resistance, such as the butterfat rate [PPARGC1A], milk production [B4GALT1], immunity [IL2 and NFATC3], and mastitis resistance [ITSN2]." (PMID 35422847, 2022).
mental disorder (1 paper, 2018). A disease that has its basis in the disruption of mental process. "We show for the first time in a large sample that the mRNA expression of FZD7 and NFATC3, two highly relevant Wnt signaling pathway genes, is significantly increased in patients with severe mental disorders compared to HCs." (PMID 29507296, 2018).
Myocardial fibrosis (1 paper, 2023). "In conclusion, the present study demonstrated that diabetes promotes myocardial fibrosis by activating the CaN/NFATc3/EZH2 pathway." (PMID 37735624, 2023). "In summary, our research demonstrated that CaN/NFATc3 played a crucial role in the process of myocardial fibrosis induced by diabetes." (PMID 37735624, 2023). "This study aimed to investigate the effects of the CaN/NFATc3 pathway in DM-related myocardial fibrosis and to clarify the relationship between the CaN/NFATc3 pathway and EZH2 in DM-related myocardial fibrosis in vitro and in vivo." (PMID 37735624, 2023). "Diabetes can possibly promote myocardial fibrosis by activating of CaN/NFATc3/EZH2 pathway." (PMID 37735624, 2023). "The inhibition of the CaN/NFATc3 pathway alleviated myocardial fibrosis." (PMID 37735624, 2023). "Based on those findings, we demonstrated that CaN/NFATc3/EZH2 pathway may contribute to the process of myocardial fibrosis induced by DM, suggesting that pharmacological inhibition of CaN/NFATc3/EZH2 pathway may become an effective therapeutic strategy against myocardial fibrosis in diabetes." (PMID 37735624, 2023). "Thus, the present study investigated whether CaN/NFATc3/EZH2 pathway plays a role in diabetic myocardial fibrosis, thereby presenting a new direction for prevention and treatment of myocardial fibrosis of diabetic patients." (PMID 37735624, 2023). "The aim of this study is to investigate the underlying role of calcineurin/nuclear factor of activated T cell 3 (CaN/NFATc3) pathway and the Enhancer of zeste homolog 2 (EZH2) in diabetes-related myocardial fibrosis." (PMID 37735624, 2023). "Nevertheless, the role of the CaN/NFATc3 pathway and whether EZH2 may be regulated by the CaN/NFATc3 pathway in diabetes-induced myocardial fibrosis is not fully understood." (PMID 37735624, 2023).
Nephropathy (1 paper, 2025). A nonspecific term referring to disease or damage of the kidneys. "Despite these significant findings, our study does not explore the role of the NFATc3/LRRC55/BK channel axis in other types of nephropathy, necessitating further research to validate its broader implications." (PMID 40520074, 2025).
oral cancer (1 paper, 2021). "NFATC3 plays an important role in retaining stemness via NFATC3/OCT4 signaling and its overexpression increases tumorigenesis in oral cancer." (PMID 33816459, 2021).
oropharyngeal cancer (1 paper, 2021). Carcinoma, predominantly squamous cell, arising from the epithelial cells of the oropharynx. "According to their data Orai1 has been highly expressed in oral/oropharyngeal cancer and activates downstream molecule NFATc3 which proposes Orai1/NFAT axis to have importance on CSC in OPC." (PMID 34359786, 2021).
ovarian carcinoma (1 paper, 2017). A malignant neoplasm originating from the surface ovarian epithelium. "Hypermethylation of genes like ASS1, MLH1, and MSX1, and WNT pathway-related genes including DVL1, NFATC3, and SFRP5 was related to poor outcome of ovarian cancer patients treated with platinum-based chemotherapy." (PMID 28641578, 2017).
pancreatic ductal adenocarcinoma (1 paper, 2022). An infiltrating adenocarcinoma that arises from the epithelial cells of the pancreas. "Here, we have demonstrated that NFATc3 is activated in human pancreatic ductal adenocarcinoma (PDAC) cells and that excessive activation of NFATc3 is correlated to advanced stages of PDAC and short survival time of PDAC patients." (PMID 35484132, 2022). "However, the role of NFATc3 in pancreatic ductal adenocarcinoma (PDAC) remains unclear." (PMID 35484132, 2022).
pericardial effusion (1 paper, 2011). Fluid collection within the pericardial sac, usually due to inflammation. "It has been previously shown that dual deletion of NFATc3 and NFATc4 causes thin ventricles, decreased proliferation of ventricular myocytes and pericardial effusion culminating in embryonic lethality." (PMID 21779394, 2011).
renal carcinoma (1 paper, 2018). A carcinoma arising from the epithelium of the renal parenchyma or the renal pelvis. "Collectively, As2O3 treatment may affect the Wnt/β-catenin pathway through decreasing the expression of NFATC3 in renal cancer." (PMID 29633893, 2018).
tongue cancer (1 paper, 2019). A malignant neoplasm affecting the tongue. "Lastly, to confirm the importance of elevated NFATc3 during oral carcinogenesis, we utilized a carcinogen-induced tongue cancer mouse model which was demonstrated in our publication." (PMID 31040921, 2019).
tooth agenesis (1 paper, 2017). A tooth disease characterized by failure to develop one or more missing teeth. "In summary, we found that novel variants in previously reported causal genes appear to mainly contribute to tooth agenesis of the anterior region, and the research using exome sequencing suggested the association between FAM65A, NFATC3 and CDH23 or SMIA." (PMID 28265457, 2017).